ROMO1 (reactive oxygen species modulator 1)
Diseases named in the same sentence as ROMO1 in open-access papers (continued):
Sharing a sentence is not in itself a finding about the gene and the disease.
ovarian carcinoma (3 papers, 2022 to 2026). A malignant neoplasm originating from the surface ovarian epithelium. "This study aimed to evaluate trefoil factor 3 (TFF3), secreted frizzled-related protein 4 (sFRP4), reactive oxygen species modulator 1 (Romo1) and nuclear factor kappa B (NF-κB) as diagnostic and prognostic markers of endometrial cancer (EC) and ovarian cancer (OC)." (PMID 35461390, 2022). "ZIF-DHA seem to effectively decrease the ROMO1 expression, generating the apoptotic cell death in ovarian cancer cells." (PMID 37386404, 2023). "ROMO1 expression in ovarian cancer cells became more difficult to degrade, as evidenced by the reduced protein expression being mitigated and the shift of the thermal melting curve to the right." (PMID 37386404, 2023). "Overexpression of ROMO1 in ovarian cancer cells significantly reversed the cellular ROS-generation induced by ZIF-DHA, as well as the pro-apoptosis effects." (PMID 37386404, 2023). "All these results collectively suggested that ZIF-DHA NPs generated the apoptotic cell death with a significant decrease of ROMO1 in ovarian cancer cells." (PMID 37386404, 2023). "Moreover, the c2.all.v2023.1.Hs.symbols in GSEA further defined the important values of ROMO1 in ZIF-DHA-treated ovarian cancers." (PMID 37386404, 2023). "However, ROMO1 expression was only slightly suppressed in ovarian cancer cells with the DHA treatment." (PMID 37386404, 2023).
bladder cancer (2 papers, 2021 to 2024). "In that study, the miR-4492/Romo1 axis was shown to regulate proliferation, migration, and tumor invasion of bladder cancer cells." (PMID 34956890, 2021).
COVID-19 (2 papers, 2023 to 2024). A disease caused by infection with severe acute respiratory syndrome coronavirus 2. "Another factor to consider is that the TNF-α and NF-κB pathways are related to ROMO1, COVID-19, and oxidative stress." (PMID 38622314, 2024). "Based on this, the researchers concluded that understanding the exact molecular mechanisms of ROMO1 in the pathogenesis of COVID-19 could pave the way to finding better therapeutic strategies." (PMID 38622314, 2024). "In conclusion, it is hypothesized that COVID-19 may increase oxidative stress by affecting ROMO1." (PMID 38622314, 2024).
diabetic (2 papers, 2017 to 2020). "In our study, we also observed increased expression of ROMO1 in diabetic kidney which was mitigated following GYY treatment suggesting that the effect of GYY in ROS mitigation was in part due to inhibition of ROMO1 expression." (PMID 28883608, 2017).
lymph node metastasis (2 papers, 2017 to 2020). "By multivariate analysis, lymph node metastasis (HR: 3.733, 95% CI: 1.520–9.169), higher LNR (HR: 2.329, 95% CI: 0.997–5.441), and higher Romo1 expression (HR: 3.198, 95% CI: 1.376–7.436) were significantly related to poorer OS." (PMID 28472059, 2017). "By multivariate analysis with Cox’s proportional hazard regression model, lymph node metastasis (HR: 4.671, 95% CI: 1.655–13.185), higher LNR(HR: 4.009, 95% CI: 1.585–10.141), and high Romo1 expression (HR: 2.735." (PMID 28472059, 2017). "With univariate analysis, patients who had no lymph node metastasis (p = 0.002) and lower LNRs (p = 0.011) had better OS, and the high Romo1 group had poorer OS (195.8 vs 158.3 months, p = 0.001)." (PMID 28472059, 2017). "By multivariate analysis with Cox’s proportional hazard regression model, lymph node metastasis (HR: 2.731, 95% CI: 1.525–4.888), higher LNR (HR: 3.582, 95% CI: 2.048–6.265), and high Romo1 expression (HR: 2.133, 95% CI: 1.167–3.896) were significantly related to poorer DFS." (PMID 28472059, 2017).
prostate carcinoma (2 papers, 2022 to 2024). A carcinoma that arises from epithelial cells of the prostate gland. "Another study reported that ROMO1 expression in prostate cancer was also associated with immune cells infiltrating the tumor, leading to changes in the tumor microenvironment and further increasing tumor heterogeneity." (PMID 39727991, 2024). "Nevertheless, ROMO1 has not been reported in the tumor microenvironment as well as in the development of prostate cancer." (PMID 34996995, 2022).
type 2 diabetes (2 papers, 2017 to 2020). "We aimed to examine the role of the rs6060566 polymorphism of the reactive oxygen species modulator 1 (ROMO1) gene in the development of myocardial infarction (MI) in Caucasians with type 2 diabetes (T2DM)." (PMID 33302957, 2020).
autoimmune disease (1 paper, 2025). A disorder resulting from loss of function or tissue destruction of an organ or multiple organs, arising from humoral or cellular immune responses of the individual to their own tissue constituents. "ROMO1 exhibited varying associations with monocytes across the three autoimmune diseases (RA, Cor = 0.20, P = 0.037; MS, Cor = 0.41, P = 3.51 × 10− 3; T1D, Cor=-0.43, P = 3.93 × 10− 3)." (PMID 40254686, 2025). "Taken together, these results indicate that ROMO1 could be a potential diagnostic marker in RA, MS, and T1D, with varying degrees of performance across these autoimmune diseases." (PMID 40254686, 2025). "Furthermore, two-sample Mendelian randomization (MR) analysis using genome-wide association studies (GWAS) data demonstrated that ROMO1 could regulate epitopes on monocytes, potentially lowering autoimmune disease risk." (PMID 40254686, 2025). "Considering RA, MS and T1D as autoimmune diseases in which immune cells play a key role in the pathological process, and our analysis revealed that ROMO1 showed significant correlation with monocytes in all three diseases." (PMID 40254686, 2025). "Our analysis consistently identified ROMO1 as differentially expressed across these three autoimmune diseases." (PMID 40254686, 2025). "Our study also provided strong evidence for ROMO1’s involvement in the ROS pathway in these three autoimmune diseases." (PMID 40254686, 2025). "After identifying ROMO1 as a key gene in three autoimmune diseases, we conducted a single gene GSEA." (PMID 40254686, 2025). "Particularly the correlation heatmaps between ROMO1 and the immune cells in three diseases further confirmed the critical role of ROMO1 in the pathogenesis of these autoimmune disorders." (PMID 40254686, 2025). "Initially, through differential gene expression analysis combined with LASSO regression, we found that ROMO1 was significantly differentially expressed in the whole blood transcriptome of the three autoimmune diseases." (PMID 40254686, 2025). "Importantly, ROMO1 and IL2RA (Cor = -0.73, P < 0.001) exhibited significant correlations in autoimmune diseases." (PMID 40254686, 2025).
cervical disease (1 paper, 2025). "This study provides a broad overview of how ROMO1 behaves across the main stages of cervical disease." (PMID 41515519, 2025).
cervical intraepithelial neoplasia (1 paper, 2025). "We investigated ROMO1 protein levels using immunohistochemistry in invasive cervical squamous-cell carcinomas, cervical intraepithelial neoplasia (CIN I, II, and III) lesions, and healthy cervical epithelium." (PMID 41515519, 2025).
chlamydial infection (1 paper, 2022). "Additionally, ROS generated by chlamydial infection may influence mitochondrial dynamics by deactivating ROS modulator 1 (ROMO1), a protein that modulates the function of the OPA1 protein." (PMID 35321312, 2022).
coronary artery stenosis (1 paper, 2020). "The carriers of the C allele of the ROMO1 rs6060566 had a threefold increased likelihood of having 50–75% coronary artery stenosis (Adjusted OR = 3.27, 95% CI 1.16–9.20)." (PMID 33302957, 2020). "The carriers of the C allele of the ROMO1 rs6060566 had a threefold increased likelihood of having coronary artery stenosis (Adjusted OR = 3.27, 95% CI 1.16–9.20)." (PMID 33302957, 2020).
depression (1 paper, 2025). "The gene ROMO1 was within a genome-wide significant locus for trainability in dogs and associated with intelligence, depression, irritability, and sensitivity/hurt feelings in humans." (PMID 41284867, 2025). "The gene ROMO1 was associated in dogs with trainability and in humans with cognitive performance and intelligence, and also with depression, irritability, sensitivity or hurt feelings." (PMID 41284867, 2025).
Dupuytren’s disease (1 paper, 2018). "The expression of nicotinamide adenine dinucleotide phosphate oxidase oxidase-1 and nicotinamide adenine dinucleotide phosphate oxidase-4 as well as reactive oxygen species modulator 1, an oxidatively damaged protein, was also higher in the Dupuytren’s disease group than in the control group." (PMID 29880057, 2018).
dysplasia (1 paper, 2025). A usually neoplastic transformation of the cell, associated with altered architectural tissue patterns. "The marked difference between normal epithelium and CIN, together with the graded increase across CIN categories, indicates that ROMO1 may help distinguish reactive epithelial changes from true dysplasia." (PMID 41515519, 2025).
head and neck cancer (1 paper, 2021). A primary or metastatic malignant neoplasm affecting the head and neck. "Reactive oxygen species modulator 1 (Romo1) was first identified in 2006 in a patient with head and neck cancer who was resistant to chemotherapy after recurrence." (PMID 34956890, 2021).
hypertrophic cardiomyopathy (1 paper, 2024). A condition in which the myocardium is hypertrophied without an obvious cause. "NDUFB1 and NDUFB2 are associated with altered cardiac energetics and mitochondrial dysfunction in patients with hypertrophic cardiomyopathy, and ROMO1 is an essential redox-dependent regulator of mitochondrial dynamics." (PMID 38396938, 2024).
hypothyroidism (1 paper, 2023). Abnormally low levels of thyroid hormone. "This possible condition is strengthened when we see an increase in the expression of the mitGene ROMO1 in hypothyroidism." (PMID 37249456, 2023). "In our study, BLOC1S1 and also ROMO1 were up-regulated in all the scenarios: in hypothyroidism, survivors and non-survivors." (PMID 37249456, 2023).
intestinal cancer (1 paper, 2024). "Correlation analysis was performed between the expression of ROMO1 in intestinal cancers and molecular or immune subtypes from the TISIDB." (PMID 39727991, 2024).
invasive carcinoma (1 paper, 2025). A carcinoma that is not confined to the epithelium, and has spread to the surrounding stroma. "ROMO1 expression in invasive carcinoma was evaluated using an H-score scale." (PMID 41515519, 2025). "Therefore, we investigated ROMO1 expression in normal cervical epithelium, CIN, and invasive carcinoma to determine whether oxidative stress markers correlate with disease progression." (PMID 41515519, 2025).
lung adenocarcinoma (1 paper, 2021). A carcinoma that arises from the lung and is characterized by the presence of malignant glandular epithelial cells. "In this study, we evaluated whether tissue Romo1 expression was associated with clinical outcomes in epidermal growth factor receptor (EGFR)-mutated lung adenocarcinoma treated with tyrosine kinase inhibitors (TKIs)." (PMID 34956890, 2021). "Our study demonstrated that high Romo1 expression was significantly associated with poor PFS and OS in patients with EGFR-mutant lung adenocarcinoma treated with frontline targeted therapy." (PMID 34956890, 2021). "In this study, we aimed to determine the clinical implications of Romo1 expression in patients with epidermal growth factor receptor (EGFR)-mutant lung adenocarcinoma treated with first-line tyrosine kinase inhibitors (TKIs)." (PMID 34956890, 2021).
skin tumors (1 paper, 2020). "ROMO1 is found upregulated in many tumor types, including head and neck, colorectal, and skin tumors." (PMID 32019183, 2020).
ulcerative colitis (1 paper, 2020). An inflammatory bowel disease involving the mucosal surface of the large intestine and rectum. "In this regard, the further studies of Romo1 involvement in CRC carcinogenesis with ulcerative colitis should be addressed." (PMID 32825500, 2020).
tumor (23 papers, 2017 to 2025). "ROMO1, a mitochondrial protein involved in ROS regulation, is known to be overexpressed in several neoplastic cells and implicated in tumour invasion and progression." (PMID 41042696, 2025). "Tumor immune infiltration analysis showed that ROMO1 expression in COAD, LIHC, PAAD, and STAD was associated with the infiltration of immune cells (B cells, CD4+ T cells, CD8+ T cells, neutrophils, macrophages, and dendritic cells)." (PMID 39727991, 2024). "In conclusion, our systematic analysis of the TCGA database supported by array-based and sequence-based PCa data has identified ROMO1, a key gene closely associated with the PCa tumor microenvironment, and the essential signaling pathways involved." (PMID 34996995, 2022). "Romo1 overexpression in tumor tissue was significantly associated with poor response and clinical outcomes in patients with advanced NSCLC treated with platinum doublets." (PMID 34956890, 2021). "To further confirm the expression of Romo1 in tumor-associated immune cells, we performed the immunofluorescence analysis and found that the expression of Romo1 in CD11b+ cells within tumor tissues was significantly higher than paratumor tissues." (PMID 31945745, 2020). "Romo1 overexpression in tumor tissue was associated with a high lymph node ratio between the metastatic and examined lymph nodes (p = 0.025)." (PMID 28472059, 2017). "Beyond HPV-associated cancers, ROMO1 plays a significant role in the biology of other tumor types." (PMID 41148844, 2025). "ROMO1 has become a possible marker of a high-ROS, high-risk tumor phenotype in a number of cancers." (PMID 41515519, 2025). "Since mitochondrial ROS are associated with tumor invasion, the researchers investigated whether ROMO1, a known inducer of mitochondrial ROS, plays a role in HCC cell invasiveness." (PMID 40427422, 2025). "In addition, ROMO1 has been found to be closely associated with tumor-infiltrating immune cells in gastrointestinal cancers." (PMID 39727991, 2024). "Moreover, ROMO1 expression was closely associated with immune infiltration and may play a role in the regulation of tumor immunity." (PMID 39727991, 2024). "Taken together, our data identify ROMO1 as a dynamic biomarker of cervical neoplasia, marking the oxidative surge of early transformation and its attenuation with tumor advancement." (PMID 41515519, 2025). "Median values of ROMO1 promoter methylation level for normal and tumor tissue COAD (median: 0.033, 0.035), ESCA (median: 0.029, 0.031), LICH (median: 0.035, 0.034), PAAD (median: 0.03, 0.032), and STAD (median: 0.037, 0.032)." (PMID 39727991, 2024). "On the contrary, to evaluate the presence of reactive oxygen species, such as the production of free radicals, as a consequence of the marked inflammatory process promoting tumor microenvironment, the concentration of ROMO-1 was estimated using an ELISA kit." (PMID 39200219, 2024). "At the same time, Trox reduced the concentration of ROMO1 compared to untreated 8305C control cells, reducing the production of free radicals, as a consequence of the inflammatory state that favors the tumor microenvironment." (PMID 39200219, 2024). "Meanwhile, we incorporated PCa data from GETx that found significant upregulation of ROMO1 in tumor tissues from GEPIA database." (PMID 34996995, 2022). "Romo-1 has been found in various neoplasm cells, responsible for the invasion and progression of cancer cells." (PMID 35461390, 2022). "In the present study, we selected the Wilcoxon test and found that ROMO1 was highly expressed in tumor tissue and significantly different from normal tissue; we also found that the four identified tumor subtypes were significantly different." (PMID 34996995, 2022). "Several reports have demonstrated that endogenous ROS levels generated by ROMO1 are required for normal and tumor cell proliferation." (PMID 34915903, 2021). "Human monocytes and macrophages have shown an overexpression of the protein Romo1 in case of tumor disease." (PMID 34610786, 2021).
tumor (continued). "Romo1 expression in tumor tissues was examined by immunohistochemistry and evaluated by histologic score." (PMID 34956890, 2021). "It has been reported that expression of reactive oxygen species modulator 1 (Romo1) increased cellular reactive oxygen species (ROS) production and contributed to tumor progression (22, –, 24)." (PMID 32291307, 2020). "The tumor mass size in TRAIL-treated Romo1-silenced group was significantly smaller compared to other groups." (PMID 32825500, 2020). "Combined treatment of TRAIL and Romo1 inhibition demonstrated anti-tumor effects compared with other groups." (PMID 32825500, 2020). "Increased expression of ROMO1, firstly identified in tumour cells, increases ROS production, leading to oxidative stress and cell death." (PMID 33302957, 2020). "Based on the results of the in vitro experiments, we investigated the combined effect of TRAIL and Romo1 inhibition in tumor xenograft model in vivo." (PMID 32825500, 2020). "We examined Romo1 expression in resected tumor tissues immunohistochemically and assessed it with histological scores." (PMID 28472059, 2017). "Alternatively, tumor progression may shift metabolic needs, reducing the necessity for ROMO1-mediated ROS control." (PMID 41148844, 2025). "The cumulative effect of viral oncoprotein activity and ROMO1 dysregulation contributes to tumor progression and creates a redox-vulnerable state that may be exploited therapeutically." (PMID 41148844, 2025). "This pattern suggests that ROMO1 may be upregulated initially to buffer HPV-induced oxidative stress, but downregulated later as the tumor progresses and accumulates additional mutations." (PMID 41148844, 2025). "This integrative sequence—HPV oncoproteins → metabolic reprogramming → mitochondrial fragmentation → ROMO1 modulation → redox imbalance and tumor progression—captures the interplay between viral transformation, mitochondrial structure and function, and disease evolution." (PMID 41148844, 2025). "Therefore, oxidative stress, promote tumor cell invasion through Romo-1 expression and constitutive NF-κB activation." (PMID 35461390, 2022). "Moreover, we found that ROMO1 was highly expressed in both tumor and normal tissues after immunohistochemistry." (PMID 34996995, 2022). "In conclusion, upregulation of ROMO1 promotes tumor growth and cell aggressiveness in HB." (PMID 34512752, 2021). "Romo1 was considered to participate in tumor growth and invasiveness." (PMID 31945745, 2020). "We performed TUNEL assay of tumor tissues obtained from the mice to investigate whether Romo1 inhibition sensitizes TRAIL-induced apoptosis." (PMID 32825500, 2020). "Then we asked whether the high expression of Romo1 occur in the immune cells within tumor microenvironment." (PMID 31945745, 2020). "Considering that CD11b mainly express in monocytes/macrophages and neutrophils and that the expression of Romo1 in neutrophils was close to negative, this result suggested that Romo1 expressed in a relatively high level in tumor-associated macrophages." (PMID 31945745, 2020). "Next, the study evaluated whether reduced ROMO1 expression impacted tumor cell invasion." (PMID 40427422, 2025). "This raises the possibility that ROMO1 modulation may contribute to tumor progression." (PMID 41148844, 2025). "In addition, knockdown of ROMO1 was found to suppress tumor formation in vivo." (PMID 34512752, 2021). "Moreover, ROMO1 is involved in cell proliferation, cell apoptosis, it is thought to have a role in replicative senescence as well as in carcinogenesis and tumour progression." (PMID 33302957, 2020). "In our study, we found that the overexpression of Romo1 promoted macrophage polarization toward M2 phenotype, which may be an important mechanism leading to the suppressed T cell response within tumor microenvironment in those mice transduced with Romo1-overexpressed bone marrow cells." (PMID 31945745, 2020).